BANP (BTG3 associated nuclear protein)
Description:
Controls V(D)J recombination during T-cell development by repressing T-cell receptor (TCR) beta enhancer function (By similarity). Binds to scaffold/matrix attachment region beta (S/MARbeta), an ATC-rich DNA sequence located upstream of the TCR beta enhancer (By similarity). Represses cyclin D1 transcription by recruiting HDAC1 to its promoter, thereby diminishing H3K9ac, H3S10ph and H4K8ac levels. Plays a role in the regulation of alternative splicing. Binds to CD44 pre-mRNA and negatively regulates the inclusion of CD44 proximal variable exons v2-v6 but has no effect on distal variable exons v7-v10.
Synonyms: BEND1; SMAR1; SMARBP1; FLJ20538; DKFZp761H172; FLJ10177
Tractability: PROTAC: UniProt records ubiquitination sites on it; ubiquitination databases record sites on it; its protein half-life has been measured.
Gene: Protein-coding gene on chromosome 16 (87,949,127 to 88,077,321, forward strand). Ensembl gene ENSG00000172530.
Subcellular location: Nucleus; Nucleus speckle; Cytoplasm
Subcellular location (Human Protein Atlas): Nucleoplasm; Nuclear bodies
Pathways (Reactome):
Cell-Cell communication: Degradation of CDH1
Gene Ontology:
Molecular function: protein binding; DNA binding
Cellular component: nuclear body; nucleoplasm; nucleus; cytoplasm; nuclear speck
Genetic constraint (gnomAD): Loss-of-function variants: 9 observed, 51.79 expected, observed/expected ratio (o/e) 0.17, 90% interval 0.1 to 0.3. The upper end of that interval is the gene's LOEUF score, 0.3, which puts it in group 1 of 6, group 1 being the genes least tolerant of losing a copy. Missense variants: 440 observed, 621.06 expected, observed/expected ratio (o/e) 0.71, 90% interval 0.65 to 0.77. Synonymous variants: 293 observed, 266.68 expected, observed/expected ratio (o/e) 1.1, 90% interval 1 to 1.21.
Homologues: Orthologues: chimpanzee BANP (98% identical), macaque BANP (97% identical), mouse Banp (91% identical), dog BANP (90% identical), pig BANP (90% identical), rat Banp (80% identical), rabbit BANP (79% identical), guinea pig BANP (78% identical), tropical clawed frog banp (74% identical), zebrafish banp (66% identical).
Diseases named in the same sentence as BANP in open-access papers:
BANP is named in the same sentence as 35 diseases in open-access papers, as found by Europe PMC text mining. Sharing a sentence is not in itself a finding about the gene and the disease. The quoted sentences say what the papers report.
breast carcinoma (11 papers, 2007 to 2024). "The aberrant expression of BANP has been closely associated with breast cancer and acute myeloid leukaemia; thus, BANP has the potential to be a prognostic/diagnostic marker and therapeutic target." (PMID 39225042, 2024).
colorectal cancer (8 papers, 2017 to 2022). A primary or metastatic malignant neoplasm that affects the colon or rectum. "The knockdown of circ-BANP could significantly attenuate the proliferation of colorectal cancer cells." (PMID 29096676, 2017). "The results demonstrated that dysregulated circ-BANP appears to have an important role in colorectal cancer cells and could serve as a prognostic and therapeutic marker for colorectal cancer." (PMID 28969093, 2017). "Circ-BANP was also found to be over-expressed in colorectal cancer." (PMID 29096676, 2017).
keratoconus (5 papers, 2014 to 2026). A degenerative, structural disorder of the eye, characterized by a cone-shaped protrusion of the cornea. "Another recent multi-omics analysis reported methylation changes in LOX, SMAD3, KLF5, HOXB1, and BANP among others in keratoconus tissue." (PMID 41595486, 2026). "ZNF469 (which encodes a large zinc-finger protein) was initially known for its role in the recessive Brittle Cornea Syndrome, but a common SNP (rs9938149) near ZNF469/BANP also shows genome-wide significance for keratoconus and CCT." (PMID 41595486, 2026). "We found evidence that SNPs associated with keratoconus often alter methylation of many genes, including LOX, PDDC1, SMAD3, HOXB1, KLF5, and BANP." (PMID 33649486, 2021). "Similarly, other candidate genes identified by GWAS including HGF, RAB3GAP1, LOX, MPDZ, NFIB, BANP, and ZNF469 may be important risk factors for keratoconus and require replication studies in other populations." (PMID 25254113, 2014).
lung carcinoma (5 papers, 2018 to 2022). "In another study, LARP1 was established as a target of miR-503 and further regulated by circ-BANP to promote lung cancer progression." (PMID 35785179, 2022). "For instance, circ-BANP accelerated the development of lung cancer through targeting miR-503/LARP1 axis." (PMID 33393621, 2021). "Mechanism study indicates that circ-BANP can play a regulatory role in the development of lung cancer through the miR-503/LARP1 signaling pathway." (PMID 30400981, 2018). "CircMAN2B2, hsa_circ_0007385, and circ-BANP were upregulated in lung cancer tissues." (PMID 30400981, 2018). "The circ-BANP-mediated miR-503/LARP1 signaling pathway promotes the proliferation and metastasis of lung cancer." (PMID 35342419, 2022).
atherosclerosis (1 paper, 2024). A disease characterized by the build-up of fatty material and calcium deposition in the arterial wall resulting in partial or complete occlusion of the arterial lumen. "These inflammatory processes are crucial in the development and progression of atherosclerosis, further complicating the interpretation of the effects of circ-BANP and circHIPK3." (PMID 39219419, 2024). "Thus, while circ-BANP and circHIPK3 are significant players in cellular processes related to atherosclerosis, their precise roles in the disease's progression remain ambiguous." (PMID 39219419, 2024).
Huntington disease (1 paper, 2015). Huntington disease (HD) is a rare neurodegenerative disorder of the central nervous system characterized by unwanted choreatic movements, behavioral and psychiatric disturbances and dementia. "G-4 genes included 6 genes: Btg3 associated nuclear protein (Banp), Ephx2, retinoid X receptor gamma (Rxrg), Ryr1, RNA-binding protein fox-1 homolog 1 (Rbfox1) and Zbtb16 categorized as ‘hereditary disorder (Huntington's disease)'." (PMID 26165378, 2015).
renal carcinoma (1 paper, 2024). A carcinoma arising from the epithelium of the renal parenchyma or the renal pelvis. "In summary, these results suggested that ZNF471 could interact with BANP in renal cancer cells and inactivate PI3K/AKT/mTOR signalling, thus further suppressing the malignant phenotype of RCC cells." (PMID 38169650, 2024). "In addition, the results of our cell biology functional experiments showed that BANP can inhibit the proliferation and metastasis of renal carcinoma cells, and induce apoptosis and cell cycle arrest in renal carcinoma cells." (PMID 38169650, 2024). "To verify the biological function of BANP in renal cancer, we transfected a BANP-specific siRNA into renal cancer cells (786-O and ACHN) stably transfected with ZNF471 to knock down the expression of BANP, and then qRT-PCR was used to determine the knockdown efficiency after transfection." (PMID 38169650, 2024).
tumor (27 papers, 2007 to 2024). "Among cell-cycle regulators, BTG3-associated nuclear protein and cyclin-dependent kinase inhibitor 1B are involved in the cell-cycle G1/S transition, playing tumor-suppressor roles." (PMID 35629968, 2022). "BANP is also known as SMAR1; it was originally identified as a nuclear protein that binds to matrix-associated regions possibly through its C-terminal DBD and functions as a tumour repressor." (PMID 39225042, 2024). "The main role of BANP in tumours is to regulate the cell cycle, prevent tumour metastasis and invasion through the transforming growth factor (TGF-β) pathway, and regulate cytoskeletal dynamics and the NF-κB signalling pathway." (PMID 38169650, 2024). "Downregulating the circ-BANP expression which was highly expressed in CRC inhibited tumor cell proliferation." (PMID 35783017, 2022). "Meanwhile, 10 circRNAs, including circ-BANP, circPVT1, ciRS-7, hsa_circ_0001946, hsa_circ_0007534, hsa_circ_000984, hsa_circ_0016760, hsa_circ_0020123, hsa_circ_0025033, and hsa_circ_0087862 were shown to inhibit apoptosis, further enhancing tumor viability." (PMID 33832139, 2021). "Thus, physiological functions of BANP, especially in cell-cycle regulation and tumor suppression, are still unknown." (PMID 35942692, 2022). "In addition, BANP could prevent tumour metastasis and invasion through the TGF-β pathway." (PMID 38169650, 2024). "BANP was initially identified as a nuclear MAR-binding protein and reported to function as a tumor suppressor." (PMID 35942692, 2022).
cancer (19 papers, 2007 to 2025). A tumor composed of atypical neoplastic, often pleomorphic cells that invade other tissues. "BANP (BTG3 associated nuclear protein) is a nuclear matrix attachment region binding protein (MARBP) essential for nuclear matrix binding that has been implicated in cancer." (PMID 36505804, 2022). "Our study demonstrated that several cancer-related mutations in the BEN domain of NACC1 and BANP disrupt DNA recognition, which may provide some clues for their relevance to human malignancy and may inspire us to identify new therapeutic strategies." (PMID 39225042, 2024). "Numerous other genes such as ESPL1, DOCK8, ARID3A, PFKFB4, ANKZF1, BANP and GRB7 showed elevated expression rates, some of which are known or suspected to be involved in cancer development and/or progression." (PMID 37193047, 2022).
infection (1 paper, 2022). The state of being infected such as from the introduction of a foreign agent such as serum, vaccine, antigenic substance or organism. "Among the highly upregulated genes in both infection groups were ESPL1, DOCK8, ARID3A, PFKFB4, ANKZF1, BANP and GRB7, all of which exhibited a log2 fold change of ≥1.5." (PMID 37193047, 2022).
BANP also shares sentences with these, for which no sentence is quoted: melanoma (4 papers); acute myeloid leukaemia (2); adenoma (1); anaplastic thyroid carcinoma (1); autoimmune disorders (1); breast neoplasm (1); CADASIL (1); cervical cancer (1); chronic myelocytic leukemia (1); chronic obstructive pulmonary disease (1); colitis (1); colon cancer (1); colorectal (1); diabetes (1); gastric cancer (1); non-small cell lung carcinoma (1); Obesity (1); ovarian carcinoma (1); psychiatric disorder (1); pulmonary disorders (1); renal cell carcinoma (1); respiratory diseases (1); stress-related disorder (1); ulcerative colitis (1); viral infection (1).